SIRT1 (sirtuin 1)
Diseases named in the same sentence as SIRT1 in open-access papers (continued):
Sharing a sentence is not in itself a finding about the gene and the disease.
ischemic stroke (continued). "Although most investigators have confirmed the positive role of Sirt1 in improving BBB damage in ischemic stroke, there are still some studies that contradict these findings." (PMID 37622049, 2023). "Another study demonstrated that miR-489-3p was also involved in the regulation of Sirt1 on apoptosis in ischemic stroke." (PMID 37622049, 2023). "Apart from small molecules, several pharmacological compounds have been shown to exert neuroprotective effects against ischemic stroke by activation of SIRT1 with various mechanisms, including antiapoptotic, anti-inflammatory and antioxidative effects." (PMID 36507335, 2022). "The mRNA expression levels of NLRP3, SIRT1, and IL-18 on an animal model of ischemic stroke with CPSP were measured by qRT-PCR to validate the data mining findings from GEO." (PMID 36059399, 2022). "Calycosin-7-O-β-D-glucoside (CG), a representative drug, downregulated the expression of Bax, which further suggests that CG protects against ischemic stroke by activating the SIRT1/FOXO1/PGC-1α signaling pathway." (PMID 36105479, 2022). "In recent years, SIRT1 has been reported to have protective effects against cerebral I/R injury in experimental studies of diverse ischemic stroke models, including focal, or global cerebral ischemia (GCI)." (PMID 36507335, 2022). "Numerous studies have shown that activation of SIRT1 is a neuroprotective agent for ischemic stroke through several mechanisms." (PMID 34645465, 2021). "The protective action of SIRT1 in ischemic stroke is also regulated through the negation of oxidative stress." (PMID 32727328, 2021). "SIRT1 is a potential therapeutic target against ischemic stroke as it can ameliorate the gene expression imbalance besides promoting cellular metabolism." (PMID 32727328, 2021). "Decreased mitochondrial uncoupling protein-2 (UCP2) activity and enhanced BDNF expression are other pathways mediated through SIRT1 regulation that protect neurons in ischemic stroke." (PMID 32727328, 2021). "SIRT1 mediates neuroprotection after ischemic stroke, traumatic brain injury, and neurodegenerative diseases." (PMID 34680562, 2021). "Panax notoginseng saponins are the representative bioactive agent of PN extracts, and it is widely used in the treatment of ischemic stroke, probably due to its inhibition of apoptosis via upregulation of SIRT1 and antioxidants." (PMID 33294469, 2020). "Studies of the aging brain have shown that the expression of SIRT1 decline with age, which is accompanied by a higher incidence of aging related diseases in mammals, such as ischemic stroke." (PMID 33198798, 2020). "Salvianolic acid B derived from danshen has a protective effect against ischemic stroke through the activation of SIRT1, leads to an increase of Bcl-2 and a decrease of Bax expression by inhibiting the acetylation of FOXO1, and finally inhibits the apoptosis." (PMID 33014276, 2020). "Our results indicate that Tet exerts neuroprotective effects against ischemic stroke injury partly through inhibiting the activation of the NLRP3 inflammasome via upregulating Sirt-1." (PMID 32419986, 2020). "For example, rosuvastatin was found to provide a neuroprotective effect against ischemic stroke by inhibiting the NF-κB signaling pathway through the activation of SIRT1." (PMID 33014276, 2020). "In conclusion, our results suggest that CG protects against ischemic stroke by activating SIRT1, which in turn upregulates FOXO1 and PGC-1α expression." (PMID 31885537, 2019). "Icariin (ICA), one of the major active flavonoids extracted from the Chinese medicinal herb, Epimedium brevicornum Maxim, were also proved to protect against ischemic stroke by increasing Sirt1 and PGC-1α expression." (PMID 30519156, 2018).
ischemic stroke (continued). "Further research is still needed to elucidate the full picture of the role of Sirt1 in DNA repair under ischemic stroke conditions." (PMID 30519156, 2018). "Nampt protects against ischemic stroke through rescuing neurons from death via the SIRT1-dependent AMPK pathway." (PMID 30519156, 2018). "Supporting the white matter protection by SIRT1 in ischemic stroke, studies in other neurological models demonstrate a similar SIRT1 mediated benefit." (PMID 30532738, 2018). "Although most studies suggest that Sirt1 is a protective mediator in ischemic stroke, there are still a few studies that contradict these findings." (PMID 30519156, 2018). "Resveratrol was demonstrated to protect ischemic stroke by upregulating the Sirt1-PGC-1α signaling pathways and exert an antioxidative effect under ischemic stress." (PMID 30519156, 2018). "In this review, we discuss the role and potential mechanisms by which Sirt1 protects against ischemic stroke." (PMID 30519156, 2018). "Several studies suggested that Sirt1 plays an important role in oxidative stress in ischemic stroke." (PMID 30519156, 2018). "The Sirt1/PGC-1α signaling pathway may serve as a promising therapeutic target for the regulation of mitochondrial dysfunction in ischemic stroke." (PMID 40160465, 2025). "The inhibition of NF-κB by Sirt1 may potentially mitigate the progression of neuroinflammation in ischemic stroke." (PMID 40160465, 2025). "Targeting MiRNA Sirt1 could be a promising approach to modulate apoptosis in cases of ischemic stroke." (PMID 40160465, 2025). "Studies demonstrate that the Sirt1-Bmal1 pathway also plays a crucial role in ischemic stroke, exerting regulatory effects in the early stages by modulating the expression of oxidative stress and inflammatory markers such as MDA, SOD, IL-6, and Tumor Necrosis Factor-alpha." (PMID 40527853, 2025). "Third, the relationship between Sirt1 genetic polymorphisms and ischemic stroke has not been extensively investigated, with many existing studies focusing on animal models." (PMID 40160465, 2025). "However, there is a paucity of studies investigating the relationship between Sirt1 and necroptosis following ischemic stroke, necessitating further research to elucidate their interaction." (PMID 40160465, 2025). "In any case, Sirt1 regulation of the PCD pathway may represent a novel approach to modulating PAN apoptosis in ischemic stroke." (PMID 40160465, 2025). "Therefore, it is imperative to further investigate the role of Sirt1 in ischemic stroke across various brain cell types, elucidate the precise mechanisms of action, and draw robust conclusions." (PMID 40160465, 2025). "Therefore, the potential of Sirt1 as a therapeutic target for the management of ischemic stroke is promising." (PMID 40160465, 2025). "Notably, Sirt1 induces autophagy following ischemic stroke and exerts a negative regulatory impact on this cellular process." (PMID 40160465, 2025). "The proposed “SIRT1/SIRT3 activity” may highlight a novel therapeutic perspective for the clinical management of ischemic stroke-related conditions." (PMID 38767771, 2024). "As a proof-of-concept study, this study provides a new strategy for delivering the protein-based gene therapy to the brain that bypasses the BBB and demonstrates that SIRT1 could be an attractive candidate for the treatment of ischemic stroke." (PMID 39239521, 2024). "Interestingly, Sirt1 not only can induce autophagy after ischemic stroke, but also has a negative regulatory effect on autophagy." (PMID 37622049, 2023). "Although various inhibitory mechanisms of Sirt1 on NLRP3 inflammasome have been discussed, whether Sirt1 exerts a protective effect on ischemic stroke by directly regulating NLRP3 deacetylation to inhibit pyroptosis remains unknown." (PMID 37622049, 2023). "However, SIRT1 silencing blocked these effects and exacerbated the oxidative stress that follows an ischemic stroke." (PMID 37627275, 2023).
ischemic stroke (continued). "After ischemic stroke, miR-489-3p was upregulated, while Sirt1 was downregulated." (PMID 37622049, 2023). "Furthermore, it was recently demonstrated that Sirt1 participated in the neuroprotection against ischemic stroke both in vivo and in vitro by inhibiting ferroptosis via SLC7A11, another key executor of ferroptosis." (PMID 37622049, 2023). "Importantly, several studies have confirmed that SIRT1 plays a key role in neuroprotection by inhibiting the activation of NLRP3 inflammasomes after ischemic stroke." (PMID 36105479, 2022). "Acupuncture may inhibit CPSP in an animal model of ischemic stroke by upregulating SIRT1 expression levels, inhibition of the activation of the inflammasome, and downregulating IL-18 expression levels." (PMID 36059399, 2022). "QRT-PCR results on animal models of CPSP ischemic stroke showed that the expression levels of SIRT1 were downregulated, the activation of the NLRP3 inflammasome was upregulated, and the expression levels of IL-18 were upregulated in the brain tissues of the surrounding area of the injury." (PMID 36059399, 2022). "It was demonstrated that ARC treatment could effectively suppress SIRT1-driven NLRP3 inflammasome activation by ischemic stroke in rat models." (PMID 36105479, 2022). "In addition, lncRNA Snhg8 attenuates microglia inflammatory response and blood-brain barrier damage in ischemic stroke by regulating miR-425-5p-mediated SIRT1/NF-κB signaling pathway." (PMID 35286233, 2022). "In an experiment using the middle cerebral artery occlusion (MCAO) model, salvianolic acid B (SalB), which has been proven protective against ischemic stroke in previous studies, reduces brain injury induced by ischemic stroke by activating SIRT1 to reduce apoptosis and inflammation." (PMID 36105479, 2022). "The Sirt1-AMPK pathway plays a protective role in ischemic stroke, so whether RSV ameliorates cerebral I/R injury by inhibiting the NLRP3 inflammasome through autophagy induction via Sirt1-AMPK pathway is worth studying." (PMID 34079796, 2021). "We thus hypothesized that miR-19a/b-3p function through targeting SIRT1/FoxO3 axis in ischemic stroke." (PMID 34051800, 2021). "Pharmacological modulation of SIRT1 can have a pronounced effect on the outcome of ischemic stroke." (PMID 34680562, 2021). "Studies have shown that SIRT1 plays an important role in ischemic stroke." (PMID 33841157, 2021). "Of note, activation of SIRT1 by GB has been observed in endothelial cells and ischemic stroke." (PMID 34257705, 2021). "Suppression of the inflammation by targeting miR-19a/b-3p/SIRT1/FoxO3/SPHK1 could be a promising avenue to improve the outcome of ischemic stroke." (PMID 34051800, 2021). "These phenomena raise the possibility that SIRT1 may play a crucial role on neurogenesis after ischemic stroke." (PMID 33198798, 2020). "The findings suggest that KFL may be a promising choice for the intervention of ischemic stroke and highlighted the SIRT1/P66shc signaling." (PMID 32382538, 2020). "Taken together, these findings indicate that CG alleviates OGD/R-induced damage via the SIRT1/FOXO1/PGC-1α signaling pathway, and CG maybe a promising therapeutic candidate for brain injury associated with ischemic stroke." (PMID 31885537, 2019). "Given the protective effects of CG on ischemic stroke, we hypothesized that CG protects against ischemic stroke via the SIRT1/FOXO1/PGC-1α signaling pathway." (PMID 31885537, 2019). "Some studies reported that Sirt1 is important in the protection against ischemic stroke." (PMID 30519156, 2018). "Estrogen protects against ischemic stroke via the SIRT1-dependent AMPK pathway." (PMID 30519156, 2018). "Recently, many studies have focused on the role of Sirt1 in ischemic stroke." (PMID 30519156, 2018). "In this review, we discuss the role and mechanisms of Sirt1 in the setting of ischemic stroke." (PMID 30519156, 2018).
ischemic stroke (continued). "Therefore, additional studies investigating the role of Sirt1 in ischemic stroke involving different cerebral cell types and animal models are necessary to arrive at more convincing conclusions." (PMID 30519156, 2018). "Therefore, this study aims to elucidate the mechanisms underlying the interaction between SIRT1 and necroptosis and explore the therapeutic potential of traditional Chinese medicine (TCM), specifically SPD, in targeting SIRT1 as a treatment strategy for ischemic stroke." (PMID 40008377, 2025). "Hence, the presence of Sirt1 is crucial for maintaining autophagy levels during ischemic stroke." (PMID 40160465, 2025). "Moreover, comparisons of BMAL1 and SIRT1 levels across four different time subgroups in patients (00:00–05:59, 06:00–11:59, 12:00–17:59, and 18:00–23:59) revealed that expression levels were lowest in patients with ischemic stroke onset at 6:00–11:59." (PMID 41440117, 2025). "Therefore, the Sirt1/NLRP3 signaling pathway may attenuate the development of neuroinflammation in ischemic stroke." (PMID 40160465, 2025). "Consequently, the question of whether targeting Sirt1 for the treatment of ischemic stroke by increasing its levels would be beneficial to brain tissue under ischemic stress remains a topic of debate." (PMID 40160465, 2025). "Thus, Sirt1/AMPK-mediated signaling may provide a potentially useful strategy to modulate autophagy during ischemic stroke." (PMID 40160465, 2025). "Altogether, these findings suggest that SIRT1 improves mitochondrial respiratory function by enhancing SIRT3 activity, which may illuminate the mechanism underlying the promotion of energy metabolism in treating ischemic stroke." (PMID 38767771, 2024). "Collectively, these findings evidence that SIRT1 may provide neuroprotection against CI/R-induced oxidative stress by enhancing SIRT3 activity, signifying that a proper manipulation of “SIRT1/ SIRT3 activity” may alleviate the excessive oxidative stress in ischemic stroke." (PMID 38767771, 2024). "However, further study is needed to confirm whether and how Sirt1 diminishes excitotoxicity after ischemic stroke." (PMID 37622049, 2023). "It is recently reported that EA treatment may inhibit apoptosis by regulating autophagy in the acute phase of ischemic stroke, thereby alleviating brain injury, and Sirt1 may play a crucial role in the regulation of autophagy in EA treatment for ischemic stroke." (PMID 37622049, 2023). "Therefore, Sirt1 is considered to be a therapeutic target for ischemic stroke." (PMID 36076942, 2022). "SIRT1 could be also a promising therapeutic target for ischemic stroke." (PMID 33935765, 2021). "Besides, the relationship between Sirt1 genetic polymorphism and ischemic stroke has not been researched extensively, which also needs further exploration." (PMID 30519156, 2018). "In treating ischemic stroke, RNA binding protein RPS3 regulates microglial pyroptosis and neuronal damage through the Sirt1/NLRP3 pathway." (PMID 40160465, 2025). "The expression of Sirt1/PGC-1α can be enhanced by Icariin, thereby exerting a preventive effect on ischemic stroke." (PMID 40160465, 2025). "Certain subgroups of ischemic stroke patients had the lowest expression levels of SOD, BMAL1, and SIRT1, whereas other subgroups had the highest levels of MDA, IL-6, and TNF-α." (PMID 41567643, 2025). "In an in vitro study in a mouse model of ischaemic stroke, HBO was observed to inhibit HMGB1 via SIRT1-dependent deacetylation." (PMID 40243713, 2025). "This study found a downward trend in BMAL1 and SIRT1 expression along with increased activation of oxidative stress (MDA) and inflammatory factors (IL-6, TNF-α) in patients with early-onset ischemic stroke." (PMID 38245621, 2024).
ischemic stroke (continued). "Our results showed higher MDA, IL-6, and TNF-α levels, and lower SOD, SIRT1, and BMAL1 levels in ischaemic stroke patients compared to control patients (P < 0.05)." (PMID 38245621, 2024). "Furthermore, they demonstrated that circSHOC2 in IP-ADEVs suppressed neuronal apoptosis and ameliorated neuronal damage by regulating autophagy and acting on the miR-7670-3p/SIRT1 axis, which might provide strategies for the future treatment of ischemic stroke." (PMID 37728588, 2024). "When comparing the relative expression levels of BMAL1 and SIRT1 proteins among the four subgroups, a significant decrease in BMAL1 and SIRT1 expression levels was found in patients with ischaemic stroke onset from subgroup 2 (6:00 to 11:59)." (PMID 38245621, 2024). "These clinical evidences suggest that Sirt1 has potential as a target for prevention and treatment for AIS patients, and can be used as a prognostic indicator of ischemic stroke." (PMID 37622049, 2023). "Therefore, SIRT1 could be a promising therapeutic target for ischemic stroke." (PMID 33935765, 2021). "Meanwhile, the expression of SIRT1, p-ERK1/2, p-JNK were promoted by EA at 24 h after ischaemic stroke." (PMID 33603645, 2021). "Treatment of mice with Activator III reduced the infarction volume, while the SIRT1 and SIRT2 inhibitor sirtinol increased ischemic damage both in the model of ischemic stroke and in the model of hemorrhagic stroke." (PMID 34680562, 2021). "Likewise, as an endogenous compound, APN also has the ability to activate SIRT1 and its downstream molecules, but in ischemic stroke it is unreported whether exogenous APN treatment has protective effects against oxidative stress damage via activation of SIRT1 and its downstream molecules." (PMID 28042384, 2016). "Additionally, we identified that targeting SIRT1 with TCM, such as SPD, held promise as a potential therapeutic strategy for ischemic stroke." (PMID 40008377, 2025). "Collectively, these findings evidence that the function of mitochondria is crucial in alleviating CI/R-induced neuronal damage and that the “SIRT1/SIRT3 acetylation and SIRT3 activity” may be exploited for the treatment of ischemic stroke." (PMID 38767771, 2024). "Studies have shown that TEAS, by adjusting the SIRT1/FOXO3a and SIRT1/BRCC3/NLRP3 signaling pathways following ischemic stroke, inhibits cell apoptosis, oxidative stress, and inflammation of the nerve to reduce brain damage and accelerates the recovery of neurons and some functional metabolism." (PMID 39665041, 2024). "In ischemic stroke models, SNHG8 contributes to neuronal apoptosis, microglial activation, and neuroinflammation by sponging miR-449c-5p and miR-425-5p, resulting in the downstream regulation of sirtuin 1 (SIRT1)." (PMID 38726308, 2024). "The activation of Sirt1/FOXO1 pathway by Betulinic acid, a pentacyclic triterpene acid mainly extracted from birch bark, suppressed the autophagy, which improved the brain damage after ischemic stroke." (PMID 37622049, 2023). "Based on the previous searches and reports, it was hypothesized that the significant protective effects of GP17 against ischemic stroke might be exerted via autophagy via Hif-1α/BNIP3 pathway or NAMPT-mediated pathway, namely SIRT1/2/3." (PMID 36572901, 2022). "Previous studies have shown that PDE4 inhibitors are not direct activators of SIRT1 in ischaemic stroke but can stimulate SIRT1 by activating AMPK16." (PMID 34611179, 2021). "The current study provides novel insights that possibly SIRT1, JNK, and ERK1/2 might be potential therapeutic targets to alleviate neuronal apoptosis after ischaemic stroke." (PMID 33603645, 2021). "Collectively, these data reveal that SIRT1 alleviates the CI/R-induced damage to the mitochondrial ultrastructure by enhancing SIRT3 activity and may have therapeutic potential for reducing mitochondrial structural damage from ischemic stroke." (PMID 38767771, 2024).